ENSG00000273167 (novel transcript)
Gene: Protein-coding gene on chromosome 13 (23,979,700 to 24,321,031, forward strand). Ensembl gene ENSG00000273167.
Genetic constraint (gnomAD): Missense variants: 1,035 observed, 1,227.2 expected, observed/expected ratio (o/e) 0.84, 90% interval 0.8 to 0.89. Synonymous variants: 406 observed, 475.43 expected, observed/expected ratio (o/e) 0.85, 90% interval 0.79 to 0.93.